NGF (nerve growth factor)
Diseases named in the same sentence as NGF in open-access papers (continued):
Sharing a sentence is not in itself a finding about the gene and the disease.
Obesity (30 papers, 2013 to 2025). Accumulation of substantial excess body fat. "Numerous studies in the literature propose that obesity is linked to elevated NGF levels and show that overweight, obese, and morbidly obese women, as well as women with MS, tend to exhibit higher NGF levels." (PMID 37373824, 2023). "NGF seems to play a role in several diseases related to cardiovascular risk, such as coronary atherosclerosis, obesity, T2DM, and metabolic syndrome." (PMID 25159899, 2014). "It would be tempting to speculate that in obesity NGF overexpression causes hyperinnervation, however, evidence suggests that in obesity‐related metabolic disorders NGF and brain derived neurotrophic factor signaling is reduced." (PMID 39825711, 2025). "If fat deposition is reduced in response to a suboptimal in utero environment, this is possibly mediated by factors such as NGF, and it is hypothesized to lead to an increased risk of obesity in adult life." (PMID 37373824, 2023). "Furthermore, NGF is also positively associated with salivary insulin, blood pressure, obesity, and anthropometric measures." (PMID 38202116, 2023). "Similarly, the best-known neurotrophin NGF, also recently identified as adipokines associated with obesity, exhibited a significant elevation in the OB group (11.08 ± 0.94 pg/mL; p < 0.005) in comparison with NW participants." (PMID 35626286, 2022). "The salivary concentration of BDNF and NGF was higher in obese children, and it is positively associated with anthropometric measures, suggesting that neurotrophins can be used as a non-invasive predictor of obesity-related complications in children." (PMID 35626286, 2022). "The identified variant is located close to the site of a variant (A175N) previously reported in individuals with severe early-onset obesity which was shown to disrupt the function of NGF-induced neuronal differentiation." (PMID 38297031, 2024). "We investigated the effects of a 12-week resistance exercise program with different set structures on the blood levels of BDNF, NGF, and obesity-related markers in middle-aged women with obesity." (PMID 37176576, 2023). "Since adipose tissue greatly expands during obesity and MS, it is expected that this tissue contributes to a greater extent to increasing NGF levels during the early stages of MS than in later stages." (PMID 36768281, 2023). "This 12-week study investigates the effects of resistance training with different set structures on the plasma levels of brain-derived neurotrophic factor (BDNF), nerve growth factor (NGF), and obesity-related markers in middle-aged Korean women with obesity." (PMID 37176576, 2023). "The rationale for assessing BDNF and NGF levels was to investigate the effects of resistance training on neurotrophic factors in middle-aged women with obesity." (PMID 37176576, 2023). "Alterations in NGF and/or BDNF have been associated with several pathologic manifestations, including behavioral aberrations, cognitive deficiencies, tumorigenesis, obesity, and epilepsy, as well as muscle-skeletal, inflammatory, and pain sensitivity diseases." (PMID 36831321, 2023). "A high-fat dietary intake induces p75NTR overexpression in WAT from mice, indicating that obesity can modulate NGF signaling." (PMID 36768281, 2023). "It thus appears that NGF acts as a response protein related to alterations in adipokines and inflammation that typically characterize obesity." (PMID 37373824, 2023). "In this study, we investigated the effects of different set structures of resistance exercise on BDNF and NGF blood levels in middle-aged Korean women with obesity." (PMID 37176576, 2023). "Statistical analysis was performed to analyze the best fit diagnostic value for biomarkers and the relationship of the neurotrophic levels of BDNF and NGF with obesity measures and blood pressure." (PMID 35626286, 2022).
Obesity (continued). "Obesity is the state of chronic low-grade inflammation; both murine and human adipose tissues release different inflammatory mediators, including NGF." (PMID 35626286, 2022). "The results show that BDNF and NGF concentrations were significantly increased in OB children compared with NW children, which correlates with obesity measures, indicating a correlation between neurotrophic proteins and fat mass." (PMID 35626286, 2022). "So, the protective role of NGF against inflammation and stress in MetS and obesity should be investigated in more details." (PMID 35620753, 2022). "Neurotrophin NGF concentration in adult female participants with different degrees of obesity showed a 1.4-fold increase in overweight and obese participants in comparison to normal-weight participants." (PMID 35626286, 2022). "The receiver-operating characteristics curve of BDNF and NGF is a good marker of obesity and metabolic complications with high sensitivity and specificity." (PMID 35626286, 2022). "The current study was designed to evaluate the neurotrophic proteins BDNF and NGF as the salivary marker of obesity in children." (PMID 35626286, 2022). "Today, it is well known that obesity and related CMDs, including AD, feature reduced circulating and/or local levels of NGF and BDNF." (PMID 33923652, 2021). "Supportively, blood NGF levels are upregulated in a group of women with obesity and the metabolic syndrome, while circulating adiponectin levels are lower in obese subjects." (PMID 30934765, 2019). "Other than a neurotrophic factor, NGF plays roles in obesity-related inflammation in the proliferation and survival of various cancers and in pain control." (PMID 30934765, 2019). "An experimental study shows that plasma NGF levels are increased in patients with metabolic syndrome and obesity validating our finding of NGF regulating energy metabolism." (PMID 29375393, 2017). "Meanwhile, with high fat diet-induced obesity, expressions of NGF and TrkA mRNA as well as BDNF and TrkB mRNA were presented significantly low." (PMID 24098984, 2013). "From the results of this study, it was identified that the rats with high fat diet-induced obesity had significantly lower levels of cognitive function-related protein expression (NGF, BDNF, p38MAPK)." (PMID 24098984, 2013). "It is also known from previous studies that in obese states, NGF levels increase, and by binding to the receptor trkA could increase insulin secretion and generate hyperinsulinemia in obesity conditions." (PMID 39857710, 2025). "Among them, obesity, BMI, body fat percentage, waist circumference, hip circumference, and resistin were risk factors, while apolipoprotein A1 (apoA1), high-density lipoprotein cholesterol (HDL-C), and nerve growth factor (NGF) were protective factors." (PMID 39050546, 2024). "At present, BDNF, NGF, and pro-NGF play a crucial role in the pathogenesis of a wide spectrum of neuronal and non-neuronal disorders, such as Alzheimer’s and other neurodegenerative disorders, including obesity and related CMD." (PMID 39065809, 2024). "Thus, in obesity, high NGF levels result in elevated blood lipid concentrations and increased lipogenesis." (PMID 37373824, 2023). "More information is needed to understand whether NGF signaling through p75NTR is a driver of adipose tissue dysfunction and inflammation during obesity or if it is a consequence of adipocyte hypertrophy." (PMID 36768281, 2023). "This anti-inflammatory effect of NGF could be particularly relevant during the development of chronic low-grade inflammation during obesity and MS." (PMID 36768281, 2023). "In addition, the correlation of BDNF and NGF with salivary insulin, blood pressure, and obesity measures were evaluated." (PMID 35626286, 2022). "Moreover, circulating NGF levels are upregulated in a group of women with obesity and metabolic syndrome, which are related to a low-grade systemic inflammation." (PMID 30934765, 2019).
Obesity (continued). "Levels of other adipokines, including nerve growth factor (NGF), interleukins, and TNF-α have also been reported to correlate with OAB, suggesting contributions of additional molecular mechanisms to LUTS pathogenesis in association with obesity/metabolic syndrome." (PMID 39989457, 2025). "There were a total of nine positive factors, namely, obesity, BMI, body fat percentage, waist circumference, hip circumference, HDL cholesterol, apoA1, resistin, and NGF." (PMID 39050546, 2024). "Studies have shown decreased levels of NGF and BDNF in conditions like metabolic syndrome, acute coronary syndromes, and obesity, suggesting their potential involvement in the development of atherosclerosis and metabolic disorders." (PMID 38026693, 2023). "Novel therapeutic approaches including intra-articular administration of inhibitors of key pain mediators such as NGF and TRPV-1 have yielded promising early results but are yet to be studied in the context of obesity." (PMID 38275369, 2023). "Few studies have investigated the effects of resistance training with different set structures on BDNF, NGF, adiponectin, leptin, and GLP-1 blood levels in middle-aged women with obesity." (PMID 37176576, 2023). "As shown in previous studies, a significantly positive correlation was observed between obesity measures (BMI, WC z-score, and WHtR z-score) and neurotrophins (BDNF and NGF) in our study." (PMID 35626286, 2022). "As suggested by previous studies, obesity and diseases reduces the expressions of NGF and BDNF, and it is considered that high fat diet-induced obesity affects hippocampal cognition-related factors." (PMID 24098984, 2013). "The study suggests that yoga could positively influence cellular biomarkers such as nerve growth factor (NGF), TNF-α, and interleukin-6 (IL-6), which are involved in the progression of oral cancer, obesity, and neurodegenerative disorders." (PMID 40282445, 2025). "Our findings indicate that drop-set resistance exercise interventions can increase NGF and BDNF levels in middle-aged Korean women with obesity, which may have significant clinical implications for enhancing cognitive function and mood regulation." (PMID 37176576, 2023). "Alongside NGF and BDNF alterations, hyperleptinemia and an increased number of mast cells in subcutaneous abdominal adipose tissue are also reported, shedding light on the role of these metabotrophins in the pathogenesis of obesity and related diseases." (PMID 38026693, 2023). "However, gECs showed increased expression of Fos, Fosb and Egr1 and increased expression of FGF receptor, nerve growth factor and IGF1 signaling networks in obesity." (PMID 36400935, 2022). "Nevertheless, it has not yet been described whether NGF regulates adipose tissue-residing mast cells in obesity." (PMID 36768281, 2023).
multiple sclerosis (29 papers, 2008 to 2025). A progressive autoimmune disorder affecting the central nervous system resulting in demyelination. "Elevated NGF levels have been found in the blood and tissues of patients with several autoimmune diseases, including, among others, multiple sclerosis, systemic lupus erythematosus, autoimmune thyroiditis, and chronic arthritis." (PMID 38791953, 2024). "The levels of NGF are elevated in the cerebrospinal fluid and synovial fluid of patients suffering from inflammatory and autoimmune diseases such as multiple sclerosis and rheumatoid arthritis, respectively." (PMID 38892241, 2024). "There are various reports of increased cerebrospinal fluid and cerebral NGF levels in patients with multiple sclerosis." (PMID 37998739, 2023). "Patients suffering from multiple sclerosis had significantly higher levels of urinary NGF/Cr and BDNF/Cr compared to the other two groups (8 pg/mL vs. 0.56 pg/mL vs. 1.25 pg/mg; p = 0.001; and 88.3 pg/mL vs. 5 pg/mL vs. 4.8 pg/mg; p < 0.0001; respectively)." (PMID 36766573, 2023). "Studies have revealed elevated levels of NGF in the blood and tissues of individuals affected by autoimmune diseases (thyroiditis, rheumatoid arthritis, and multiple sclerosis)." (PMID 37998739, 2023). "Evidence suggests that NGF is involved in the pathogenesis of numerous immune diseases including autoimmune thyroiditis, chronic arthritis, multiple sclerosis, systemic lupus erythematosus, mastocytosis, and chronic granulomatous disease." (PMID 37998739, 2023). "The levels of urine NGF/Cr and BDNF/Cr were associated with the etiology of NLUTD, and were found to be elevated in multiple sclerosis patients when compared to SCI and spina bifida patients." (PMID 36766573, 2023). "The blood levels of NGF have been found to be higher in various conditions, including multiple sclerosis, chronic granulomatous disease, systemic lupus erythematosus, chronic arthritis and mastocytosis." (PMID 37998739, 2023). "Elevated NGF levels are present in the CSF of patients with multiple sclerosis, in the synovial fluid of patients with rheumatoid arthritis, and in the serum of individuals with systemic erythematosus lupus." (PMID 36298702, 2022). "Enhanced NGF levels were initially found in the cerebrospinal fluid of multiple sclerosis patients, and it was shown that an increase in NGF closely follows the course of the disease." (PMID 28492466, 2017). "BDNF-secreting T cells are reduced in untreated multiple sclerosis patients and increased after interferon beta treatment, while NGF, NT-3 and NT-4 production by PBMCs in multiple sclerosis patients is enhanced in the post-relapse phase." (PMID 24223945, 2013). "Furthermore, we visualized the clustering timeline and identified multiple sclerosis, mu-opioid receptors, adenoviral vectors, arachidonic acid, T cells and nerve growth factor as the focus of early research on virus and neuroinflammation." (PMID 39021576, 2024). "As NGF showed neuroprotective activity and immunomodulatory effects, it has been suggested that new therapeutic approaches for the treatment of numerous brain disorders, including multiple sclerosis should focus on NGF and NTs." (PMID 37998739, 2023). "Interestingly, a recent article suggested a correlation between higher cerebrospinal fluid levels of iodothyronines, nerve growth factor and multiple sclerosis." (PMID 37998739, 2023). "We investigated the therapeutic potential of adipose mesenchymal stem cell (ADMSC) derived, cytochalasin B induced artificial microvesicles (MVs) expressing nerve growth factor (NGF) on a mouse model of multiple sclerosis experimental autoimmune encephalomyelitis (EAE)." (PMID 37176039, 2023). "Bone marrow mesenchymal stem cells can improve the symptoms of patients with multiple sclerosis by inhibiting the inflammatory response in the central nervous system, regulating the expression of interleukin 6, stimulating the production of nerve growth factor, and protecting axons." (PMID 35371265, 2022).
multiple sclerosis (continued). "Moreover, some findings have revealed the mediatory role of NGF in autoimmune diseases like multiple sclerosis, rheumatoid arthritis, and systemic lupus erythematosus." (PMID 33874912, 2021). "Overall, this study indicates that NGF inhibits oligodendrogenesis and myelination by down-regulating miR-219a-5p levels, suggesting a novel molecular circuitry that can be exploited for the discovery of new effectors for remyelination in human demyelinating diseases, such as Multiple Sclerosis." (PMID 33669304, 2021). "Considering this, GDNF and CDNF could be of particular interest for PD, NGF could be of particular interest for AD, and BDNF, because of its rich expression in the brain, could provide support for AD, PD, spinal cord injury, multiple sclerosis (MS), and Huntington’s disease (HD)." (PMID 37047292, 2023). "Meanwhile, NGF may be able to trigger inflammatory cascades with negative consequences on surrounding tissues because NGF levels are increased in many inflammatory disorders such as chronic arthritis and multiple sclerosis." (PMID 35054419, 2021).
schizophrenia (28 papers, 2010 to 2025). A major psychotic disorder characterized by abnormalities in the perception or expression of reality. "Additionally, prostaglandin-H2, nerve growth factor, and resistin, identified in the schizophrenia MR study, were also associated with SLE and RA." (PMID 40082977, 2025). "Schizophrenia is a chronic and progressive mental disorder caused by neurodevelopmental and neurodegenerative factors, indicating potential pathogenic processes mediated by NGF." (PMID 40783715, 2025). "We postulate that in the early stages of schizophrenia, NGF and BDNF are primarily linked to neurodevelopment, while in the chronic phase, their levels may be modulated by antipsychotic medication." (PMID 40082848, 2025). "Moreover, several studies have reported an association between the peripheral NGF levels and pathophysiological parameters of schizophrenia." (PMID 35265356, 2021). "The results of several studies indicate that GATAD2A may be one of the causal genes in the pathogenesis of schizophrenia, potentially through dopamine receptor D2 and nerve growth factor (NGF) pathways." (PMID 32934226, 2020). "Members of the neurotrophin protein family, including nerve growth factor (NGF), have been repeatedly implicated not only in the pathogenesis of schizophrenia per se, but are plausible candidates to be involved also in the development of these neuroanatomical anomalies." (PMID 31105606, 2019). "Moreover, several studies have reported associations between peripheral NGF levels and various aspects of schizophrenia pathophysiology." (PMID 31105606, 2019). "Remarkably, changes correlated with NGF serum levels manifested also in the cingulate cortex, a region that also showed volume reductions our group comparison between patients and controls and has been repeatedly implicated in the literature as morphologically altered in schizophrenia." (PMID 31105606, 2019). "NGF is detected in serum samples, and in most studies, the NGF levels in patients with schizophrenia are lower than that in healthy individuals." (PMID 40783715, 2025). "Previous investigations have demonstrated significantly reduced BDNF and NGF levels in patients with chronic schizophrenia compared to healthy controls, with NGF levels correlating with symptom severity." (PMID 40082848, 2025). "Pathway analysis of the NeuN+ TFs affected by age in the AT-schizophrenia/control cohort led to the top pathway ‘NGF-simulated transcription’ (p-value 8.04×10–8), including the TFs EGR2 and ATF2." (PMID 38648100, 2024). "Second, none of the analyzed covariates were significantly correlated with NGF serum levels in schizophrenia patients." (PMID 31105606, 2019). "In a conjunction analysis, GMV in the left midcingulate cortex (MCC) appears negatively correlated to NGF serum levels in the group of schizophrenia patients and also to be reduced compared to healthy controls." (PMID 31105606, 2019). "NGF serum levels in schizophrenia patients have been repeatedly reported to be significantly reduced when compared to healthy subjects." (PMID 31105606, 2019). "Delineating the effects of NGF levels on early brain development would be desirable in individuals that later present with schizophrenia." (PMID 31105606, 2019). "The observation that the correlations between NGF and brain structure were exclusively present in schizophrenia patients suggests an altered effect of NGF signaling in the brains of schizophrenia patients compared to controls." (PMID 31105606, 2019). "For example, a correlation was found between NGF autoantibodies in serum and total volume of the frontal lobe in schizophrenia patients." (PMID 31105606, 2019). "In schizophrenia patients, serum NGF levels were found to be positively correlated with GMV in the pons." (PMID 31105606, 2019). "This study aimed to investigate a potential correlation between NGF serum levels and brain structural differences in schizophrenia." (PMID 31105606, 2019).